NF2 (NF2, moesin-ezrin-radixin like (MERLIN) tumor suppressor)
Diseases named in the same sentence as NF2 in open-access papers (continued):
Sharing a sentence is not in itself a finding about the gene and the disease.
Vestibular schwannoma (continued). "When NF2 gene mutations lead to the loss of merlin function, Schwann cells undergo uncontrolled proliferation, resulting in the formation of vestibular schwannomas and other tumors associated with NF2." (PMID 39685944, 2024). "In contrast, conditional loss of Nf2 using Postn-Cre gives rise to vestibular Schwannomas and Schwann cell hyperplasia in dorsal root ganglion (DRG) and proximal spinal nerve roots." (PMID 39415595, 2024). "NF2, also known as Merlin, acts as a tumor suppressor and mutations in the NF2 gene lead to neurofibromatosis type 2 disease, which is characterized by the occurrence of bilateral vestibular schwannomas and other central nervous system tumors." (PMID 39160347, 2024). "C-jun expression levels were notably higher in rapidly growing NF2-associated vestibular schwannoma (VS) and in patients with slowly growing sporadic VS." (PMID 38817895, 2024). "Specifically in sporadic vestibular schwannomas, NF2 is the central factor in tumorigenesis, with anywhere from 15 to 84% of tumors harboring NF2 mutations." (PMID 39796693, 2024). "Bilateral vestibular schwannoma is the hallmark of NF2-related schwannomatosis, a rare tumour predisposition syndrome associated with a lifetime of surgical interventions, radiotherapy and off-label use of the anti-angiogenic drug bevacizumab." (PMID 37680691, 2023). "In particular, a vestibular schwannoma represents the most common intracranial tumor associated with NF2, which is typically bilateral in these patients." (PMID 37374217, 2023). "This again raised the overlap with NF2 as a number of cases developed unilateral vestibular schwannoma and met the Manchester diagnostic criteria for NF2." (PMID 35361920, 2022). "The majority of vestibular schwannoma cases carry pathogenic variants on the gene NF2 and at least one other genetic hit." (PMID 36097176, 2022). "Previous investigations have revealed that germline variants of the NF2 gene, a tumor suppressor gene located at 22q12, can cause vestibular schwannoma." (PMID 35626200, 2022). "The role of mutation screening for NF2 in all patients with a unilateral vestibular schwannoma is less certain." (PMID 34072574, 2021). "The disease neurofibromatosis 2 (NF2) is characterized by multiple nervous system tumors, including bilateral vestibular schwannomas and intracranial meningiomas (MNs), and is caused by mutations in the NF2 gene." (PMID 33273014, 2021). "Bevacizumab is currently considered the first line medical therapy for NF2-associated vestibular schwannomas in the setting of either hearing decline or tumor progression." (PMID 34885143, 2021). "In a recent meta-analysis of eight observational studies involving 161 patients with NF2-associated vestibular schwannomas, the best response to bevacizumab was partial regression in 41%, no change in 47%, and progression in 7% of the patients." (PMID 34072574, 2021). "Neither study demonstrated a radiographic response (tumor shrinkage of >20%) or hearing improvement in patients with NF2-associated vestibular schwannomas." (PMID 34885143, 2021). "NF2 is caused by germline mutations of the NF2 and is most commonly associated with bilateral vestibular schwannomas." (PMID 33669386, 2021). "Although no future trials are currently planned with lapatinib, it remains a potential agent for use in NF2-associated vestibular schwannomas." (PMID 34885143, 2021). "To date, the NFCTC has undertaken 15 trials: 4 focused on PNs, 3 on LGGs, 4 on MPNSTs, and 2 for NF2-associated vestibular schwannomas." (PMID 34885143, 2021). "Prior work demonstrated increased vascular endothelial growth factor (VEGF) expression in NF2-associated vestibular schwannomas, and initial studies utilizing bevacizumab demonstrated both decreased tumor volume and hearing improvement in a subset of patients." (PMID 34885143, 2021).
Vestibular schwannoma (continued). "Individuals with NF2 are at risk for a variety of nervous system tumors including peripheral and central schwannomas, particularly vestibular schwannomas (affecting cranial nerve VIII), multiple meningiomas, and ependymomas." (PMID 34885143, 2021). "Alternatively, the diagnosis can also be made with a documented NF2 pathologic variant along with either a unilateral vestibular schwannoma or two other distinct tumors." (PMID 34885143, 2021). "Crizotinib inhibited tumor formation by inhibition of focal adhesion kinase 1 (FAK1) and is current being tested in a phase 2 trial for progressive NF2-associated vestibular schwannomas (NCT04283669)." (PMID 34885143, 2021). "Based on the radiological evaluation, two affected subjects carrying SLC26A4 variants and one affected subject carrying NF2 variants in the GD group had bilateral enlarged vestibular aqueduct and bilateral vestibular schwannoma, respectively." (PMID 32238869, 2020). "We reviewed our experience in managing of NF2-associated vestibular schwannoma (VS) in children and young adults regarding the effect of surgery and postoperative bevacizumab treatment." (PMID 32548671, 2020). "The presence of bilateral vestibular schwannomas is pathognomonic for the disease and a major diagnostic criterion for NF2." (PMID 31161239, 2020). "In accordance with previous studies of sporadic schwannoma by next generation sequencing, NF2 was identified as the pathogenic gene in both spinal and vestibular schwannomas." (PMID 33193598, 2020). "The NF2 gene encodes merlin, a tumor suppressor protein, and vestibular schwannoma is the hallmark tumor of NF2." (PMID 29515781, 2018). "Tumor extension was greater in patients with NF2-associated vestibular schwannoma than in patients with sporadic vestibular schwannoma." (PMID 29515781, 2018). "We conclude that CXCR4 represents a potential target for a systemic therapeutic approach, especially in NF2-associated vestibular schwannomas." (PMID 29515781, 2018). "NF2-associated vestibular schwannomas often develop in younger patients, are more invasive, and are faster growing." (PMID 29515781, 2018). "A 16-year-old girl presenting with very large vestibular schwannomas with massive brain stem compression was diagnosed of NF2 due to beginning hearing loss." (PMID 30250447, 2018). "Hearing function was worse in patients with NF2-associated vestibular schwannoma than in patients with sporadic vestibular schwannoma." (PMID 29515781, 2018). "In this study, we measured the ability of ponatinib to decrease proliferation and survival of merlin-deficient HSC and vestibular schwannoma cells with NF2 mutations." (PMID 28427224, 2017). "It has been suggested that more than two mutations are necessary for vestibular schwannoma development in NF2 patients." (PMID 27921248, 2017). "The most common manifestations identified by the 579 NF2 registrants included difficulties with balance (81.3%), vestibular schwannomas (79.6%), tinnitus (74.8%), hearing loss (73.4%) and NF2-related pain (67.5%)." (PMID 28644838, 2017). "Previous evidence showed mutations of the neurofibromin type 2 gene (Nf2), encoding the tumor suppressor protein merlin, in sporadic and vestibular schwannomas affecting Schwann cells (SCs)." (PMID 27551454, 2015). "The importance of ErbB2 in NF2-associated tumors is also highlighted by recent research showing that lapatinib inhibits vestibular schwannoma growth." (PMID 24817309, 2014). "The hallmark of NF2 is bilateral vestibular schwannomas resulting from NF2 tumor suppressor gene germline mutation." (PMID 22937797, 2012). "Vestibular schwannomas (VSs) can be classified into two broad groups: unilateral sporadic vestibular schwannoma and those associated with neurofibromatosis type 2 (NF2)." (PMID 22567403, 2012).
Vestibular schwannoma (continued). "Bevacizumab, initially utilized in NF2 clinical trials for the treatment of growing vestibular schwannomas was associated with hearing improvement in a subset of patients (4/7 patients, 57%)." (PMID 23049959, 2012). "NF2 mutation analysis was performed on DNA from both peripheral blood and the vestibular schwannoma." (PMID 19772601, 2009). "Genetic analysis of vestibular schwannoma tissue revealed loss of the ring chromosome 22 and a somatic second hit in the NF2 gene on the remaining chromosome 22." (PMID 19772601, 2009). "Furthermore, a gene panel study found that around 66% of all sporadic vestibular schwannomas had a somatic NF2 mutation." (PMID 39796693, 2024). "The hallmark lesion of NF2 is a bilaterally occurring vestibular schwannoma (VS)." (PMID 36975476, 2023). "However, the mutation or inactivation of the NF2 gene is important for the tumorigenesis of sporadic vestibular schwannoma." (PMID 35626200, 2022). "While 95% of vestibular schwannomas (VSs) occur as unilateral sporadic tumors, the rest are associated with hereditary tumor syndrome neurofibromatosis type 2 (NF2), a germline mutation of the NF2 gene, and rarely, VSs appear in association with inherited mutations of other tumor suppressor genes." (PMID 36672540, 2022). "Vestibular schwannoma (VS) is benign tumors caused by the inactivation of Nf2 gene (27236462)." (PMID 33402177, 2021). "Vestibular schwannomas, including NF2-associated vestibular schwannomas, have been noted to express COX-2, and the degree of expression correlates with proliferation, indicating that COX-2 inhibition with aspirin might be a viable therapeutic." (PMID 34885143, 2021). "Therefore, surgical resection of NF2-associated vestibular schwannomas is usually considered in the setting of hearing sparing surgery, for progressive tumors once hearing has been lost or in the setting of any brainstem compression." (PMID 34885143, 2021). "NF2-associated vestibular schwannomas may have a higher risk of malignant progression following radiation therapy, complicating treatment considerations." (PMID 31161239, 2020). "Accordingly, NF2-associated vestibular schwannomas are the more aggressive tumor entity." (PMID 29515781, 2018). "In sporadic vestibular schwannomas (mean patient age, 51 years), expression was 4.25-fold higher, and in NF2-associated vestibular schwannomas (mean patient age, 33 years), expression was 4.9-times higher compared to the control group (mean patient age, 57 years)." (PMID 29515781, 2018). "Therefore, we examined the expression and spatial distribution of CXCR4 in sporadic and NF2-associated tumor tissue and evaluated its potential role as a prognostic marker for vestibular schwannoma." (PMID 29515781, 2018). "We tested ponatinib's effect on cultured human vestibular schwannoma cells with NF2 mutations." (PMID 28427224, 2017). "Vestibular schwannomas may appear unilaterally but may also appear bilaterally when associated with neurofibromatosis type 2 syndrome (NF2)." (PMID 23776562, 2013). "However, unilateral vestibular schwannomas may occur in association with schwannomatosis and hence cannot be used as an exclusion criterion to distinguish between schwannomatosis and NF2." (PMID 27921248, 2017). "Furthermore, these findings potentially explain the clinical observations that NF2 patients carrying Nf2 germline mutations, show poor recovery from postoperative facial nerve palsy, in comparison to individuals with sporadically occurring vestibular schwannomas." (PMID 27467574, 2016). "Among constitutional NF2 mutations, nonsense mutations are significantly more common than frameshift mutations in NF2 patients, whereas frameshift mutations are significantly more common than nonsense mutations among somatic NF2 mutations in sporadic vestibular schwannomas." (PMID 22295085, 2012).
Vestibular schwannoma (continued). "A brain MRI during routine follow-up revealed small enhancing foci in both internal auditory canals (IACs), which prompted concern for bilateral vestibular schwannomas and suspect NF2-related schwannomatosis (NF2-SWN)." (PMID 42088105, 2026). "Conspicuously, 1.8% of patients with apparently sporadic vestibular schwannomas actually had mosaic NF2-related SWN, whilst 3% had a germline LZTR1 PV." (PMID 40794298, 2025). "In all patients, it was found that one gene, NF2, played a major role in the development of vestibular schwannomas." (PMID 39941762, 2025). "All patients showed pathogenic gene variants located in NF2, underlining its central role as a driver in the pathogenesis of NF2-related and sporadic vestibular schwannomas." (PMID 39941762, 2025). "The etiology of SNHL in patients with vestibular schwannomas, particularly in the context of NF2-SWN, remains incompletely understood." (PMID 40895102, 2025). "Most of these individuals have neurofibromatosis type 2 (NF2), a devastating genetic syndrome resulting in multiple brain and spinal cord tumours, including bilateral vestibular schwannomas." (PMID 40251249, 2025). "This case illustrates the varied manifestations of NF2, including bilateral vestibular schwannomas and CNS tumors, with the patient presenting with hearing loss and right upper-limb weakness." (PMID 40821302, 2025). "With this aim, we generated iPSC lines with single or bi-allelic inactivation of NF2 by combining the direct reprogramming of human primary vestibular schwannoma cells, with the use of CRISPR/Cas9 NF2 gene editing." (PMID 40746735, 2025). "Bilateral vestibular schwannomas (VS) are the main feature of NF2-related schwannomatosis, but the immunological landscape of VS is poorly understood." (PMID 40140675, 2025). "Three genes centromeric to NF2 on 22q have now been found shown to account for ~ 70% of familial and ~ 30% of sporadic patients with multiple non-vestibular schwannomas: SMARCB1, LZTR1, and much less commonly DGCR8." (PMID 41160189, 2025). "Most current treatment paradigms for NF2-related vestibular schwannomas consider (micro)surgery, radiotherapy, and pharmacotherapeutic treatment with bevacizumab." (PMID 38672561, 2024). "In the mouse model for NF2-related vestibular schwannomas, we observed that as the tumors progressed, tumor-bearing mice developed ataxia." (PMID 38893082, 2024). "A multicenter, prospective study of 22 NF2 patients (15 adult; 7 pediatric) also evaluated the efficacy and toxicity of bevacizumab for vestibular schwannoma at a higher dosage (10 mg/kg every two weeks for six months)." (PMID 38672561, 2024). "After treatment, all target vestibular schwannomas showed tumor stabilization or regression, and the large majority of patients experienced improvement or stabilization of hearing and other NF2-related symptoms." (PMID 38672561, 2024). "Vestibular schwannoma (VS), benign cranial nerve sheath tumors of the vestibulocochlear nerve, lack efficacious systemic therapies, especially if they develop in a NF2-related schwannomatosis (NF2) background." (PMID 37627117, 2023). "Patients with NF2 develop widespread tumours of the central and peripheral nervous systems such as vestibular schwannomas, meningiomas, spinal ependymomas or peripheral nerve schwannomas." (PMID 36604703, 2023). "NF2–related schwannomatosis is a genetic disorder characterized byneurologic tumours, most typically vestibular schwannomas that originate on thevestibulo-cochlear nerve(s)." (PMID 37025569, 2023). "Comparative bioinformatic analyses revealed close similarities in NF2-related schwannomatosis and sporadic vestibular schwannoma tumours across the three datasets." (PMID 37680691, 2023). "Vestibular schwannoma are brain tumours found in NF2-related schwannomatosis patients and non-NF2-related schwannomatosis sporadic patients." (PMID 37680691, 2023).
Vestibular schwannoma (continued). "Significant inflammatory markers and signalling pathways were closely matched in NF2-related schwannomatosis and sporadic vestibular schwannoma, relating to the proliferation of macrophages, angiogenesis and inflammation." (PMID 37680691, 2023). "The expression of cyclooxygenase-2 (COX-2) is related to the proliferation of sporadic and NF2-related vestibular schwannoma." (PMID 37629179, 2023). "Tumour-infiltrating immune cells such as macrophages and T-cells correlate with increased vestibular schwannoma growth, which is suggested to be similar in sporadic and NF2-related schwannomatosis tumours." (PMID 37680691, 2023). "We evaluated our new analysis method through an in vivo study of patients with neurofibromatosis type 2 (NF2)-related vestibular schwannoma undergoing antiangiogenic (bevacizumab) therapy." (PMID 37765090, 2023). "Histological inflammation and angiogenesis play a role in growth of sporadic and NF2-related vestibular schwannoma." (PMID 36845735, 2023). "Bulk transcriptomic and imaging mass cytometry data identified macrophages as the most abundant immune population in vestibular schwannoma, comprising one-third of the cell mass in both NF2-related schwannomatosis and sporadic tumours." (PMID 37680691, 2023). "Epigenetic modification of NF2 genes is one of the possible mechanisms of NF2 gene inactivation in sporadic vestibular schwannomas." (PMID 35626200, 2022). "It has been reported that somatic alterations in the NF2 gene are critical factors in the pathogenesis of sporadic vestibular schwannomas." (PMID 35626200, 2022). "To date, mouse (and some zebrafish) models of MPNSTs, PNs, and OPGs have been developed for NF1 while a vestibular schwannoma model has been developed for NF2." (PMID 34885143, 2021). "This can be difficult to distinguish in patients who present initially with non-vestibular schwannomas suggestive of shcwannomatosis and later develop bilateral VS, establishing the diagnosis of NF2." (PMID 33445724, 2021). "The use of radiation therapy (radiosurgery), a common therapy for sporadic vestibular schwannomas, has declined in patients with NF2." (PMID 34885143, 2021). "A subsequent Phase II clinical trial of lapatinib for patients with NF2 and progressive vestibular schwannoma showed tumor regression and improvement of hearing in 4 of 17 patients treated." (PMID 33273014, 2021). "Multiple studies on vestibular schwannomas showed that hypermethylation of the NF2 locus, which leads to decreased expression of NF2, is a rare phenomenon." (PMID 34407809, 2021). "Patients with NF2 play a special role, authors discussed optimal treatment strategies for especially vestibular schwannomas." (PMID 33804067, 2021). "As with vestibular schwannomas, therapeutic trials have leveraged known NF2 signaling cascades but with only limited success." (PMID 34885143, 2021). "Some studies reported on the efficacy of everolimus, an oral inhibitor of the mTORC1, for progressive vestibular schwannomas in NF2 patients." (PMID 34072574, 2021). "Until recently, the presence of vestibular schwannoma excluded a diagnosis of schwannomatosis but patients with SMARCB1 and LZTR1 pathogenic variants that met neurofibromatosis type 2 (NF2) criteria have been described." (PMID 32575496, 2020). "Schwannomatosis, which shows some clinical overlap with NF2 including development of multiple non-vestibular schwannomas, was subsequently defined as a distinct nosological entity in 2005 and refined to include molecular diagnostic criteria in 2013." (PMID 31161239, 2020). "Vestibular schwannomas of NF2-patients showed a mean COX2 expression of 1.67 which was significantly lower compared to sporadic VS (ID-score 1.92, p = 0.0005)." (PMID 31291992, 2019). "Vestibular schwannomas of NF2 patients had significantly lower rates of COX2 expression (OR 0.45 (0.28–0.73), p = 0.0012)." (PMID 31291992, 2019).